IFIT3 (interferon induced protein with tetratricopeptide repeats 3)
Diseases named in the same sentence as IFIT3 in open-access papers (continued):
Sharing a sentence is not in itself a finding about the gene and the disease.
uveitis (1 paper, 2025). An inflammatory process affecting a part of or the entire uvea. "Several metaDEGs from the uveitis only group, including IFIT3, IFI44, IFITM1, MX1, TLR7 and DHRS9, and gene hubs from the modular co-expression analyses of the systemic disease-associated uveitis group are critical players in interferon-induced immune responses." (PMID 40270958, 2025).
Werner syndrome (1 paper, 2018). "Similar to senescent NHDFs, fibroblasts from a patient with Werner syndrome also showed higher expression levels of the ISGs, IFIT3, OASL, ISG15, Mx2, and IFIT27, even at earlier passages." (PMID 30455980, 2018).
infection (136 papers, 2010 to 2026). The state of being infected such as from the introduction of a foreign agent such as serum, vaccine, antigenic substance or organism. "We next evaluated the effect of mouse IFIT2 and IFIT3 expression on VSV-encoded protein levels during infection." (PMID 41093992, 2025). "Proteomic examination using DIA mass spectrometry, which has less sensitivity but better specificity and precision, detected only a large increase in IFIT‐3 protein that was associated with clinical infection detection and increasing viral N1 mRNA." (PMID 33625796, 2021). "While interferons and interferon-inducible proteins like IRF7, IFIT1, and IFIT3 are primarily associated with antiviral defence, they can also be induced in response to bacterial ligands, contributing to the resolution of the infection." (PMID 37845774, 2023). "Infection with WR-ΔE3 increased the mRNA levels of IFNα, IFNβ, and the ISGs OAS1, PKR, and IFIT3 as the infection duration increased." (PMID 40833106, 2025). "Opposed to this, IFIT3 levels were slightly increased compared to the levels seen after BADwt infection, using the latter viruses for infection." (PMID 40143353, 2025). "Infection with the IFIT3-targeting virus produced 5- to 10-fold more virus than the non-targeting control in both single-cycle and multi-cycle replication assays." (PMID 40497724, 2025). "Primary murine astrocytes significantly upregulated both IFIT-1 and IFIT-3 at 24 hours post-infection in response to N. meningitidis and S. pneumoniae across all tested MOIs." (PMID 41341589, 2025). "Similar results were observed at the transcript level on day two post-infection for antiviral genes Ifit3, Mx1, and Oas1, with SEOV inducing minimal gene expression." (PMID 39585900, 2024). "As expected, controls pretreated with DMSO prior to Cal07 or Perth09 infection induced IFIT3 at frequencies similar to what we observed previously." (PMID 39666644, 2024). "We also constructed a model of intrapulmonary injection of H1975 cells and infection with AAV5 containing IFIT3 inhibitor and confirmed that knocking down IFIT3 had the function of promoting tumor growth and increasing plasma exosome content." (PMID 39303913, 2024). "Bulk RNA sequencing of suspension organoids at 3, 7, 10, and 14 days post-infection revealed up to 26-fold time dependent promotion of interferon-stimulated genes such as IFIT3, MX1 and MX2, consistent with an innate antiviral response." (PMID 37205380, 2023). "CVA6 infection leads to the increased expression of ISGs, including Oas2, Irf7, Ddx60, Ifit3, Ddx58, and Isg15, which exhibit immunopathogenic potential and are implicated in neural inflammation." (PMID 36851724, 2023). "ISGs IFIT2 and IFIT3 were strongly expressed in both lineage infections as verified using Western blotting." (PMID 37766362, 2023). "IFIT3 has been shown to promote viral clearance in epithelial models of infection through activation of IFN regulatory factor 3–mediated (IRF3-mediated) viral protein and RNA catabolism." (PMID 37071484, 2023). "The expression heatmaps of the endothelial cell genes in the sample revealed that DCN and IFN-activated endothelial cell marker genes (Irf8, Rsad2, Ifit1, Ifit3, Iigp1) were significantly upregulated at 1 month post-infection as compared with the WT group." (PMID 36569953, 2022). "The results showed that compared to the infection control group at three time points, the expression of IFIT3 and IFIT5 was significantly enhanced by the 100 μg/mL APS treatment at the mRNA and protein levels." (PMID 36146725, 2022). "The present study showed that IFN-λ was more dominantly induced in the lung of SARS-CoV-2-infected hamsters from an early stage of infection and mediated the induction of ISGs such as Mx1, Rsad2, and IFIT3 preferentially from 3 dpi." (PMID 36524125, 2022). "Previous studies showed that overexpression of IFIT3 in Marc 145 cells decreases the HP-PRRSV replication and that gene silencing of IFIT3 increases its infection." (PMID 36146725, 2022).
infection (continued). "Most noticeably, Nsp1-K164A/H165A infection had least effects on the expressions of proinflammatory markers, such as Mx2, Ifit3, Tlr6, Cxcl10, and Nfkb1." (PMID 36357440, 2022). "Before infection, the cis-element was linked to IFIT1B and IFIT5, which were dynamically reshuffled to link with IFIT1, IFIT2, and IFIT3 after infection." (PMID 36195603, 2022). "Ectopic expression of IFIT3 restricts the infection of multiple viruses, including porcine reproductive and respiratory syndrome virus (PRRSV), swine influenza virus (SIV), herpes simplex virus-1 (HSV-1), and Kaposi’s sarcoma herpesvirus (KSHV)." (PMID 34724821, 2021). "Parental cells were treated with IFNα as a positive control, and a set of cells were infected with HAdV-C5 to determine if infection affected IFIT3 localization." (PMID 34724821, 2021). "IFIT2 knockdown affected K-bZIP expression only during KSHV de novo infection and silencing of IFIT3 increased K-bZIP expression only during lytic reactivation." (PMID 31059555, 2019). "Both classical monocytes and NK cells upregulated the ISGs IFIT2 and IFIT3 early in infection and ATAC-seq peaks were identified at sites containing ISRE motifs." (PMID 30596671, 2018). "Several apoptosis-related molecules such as caspase 3, caspase 8, caspase 9, and BAX appeared to be induced under conditions of reduced IFIT3, and the expression of these molecules was further enhanced by DV infection." (PMID 24223959, 2013). "The numerical analysis revealed that a reduction of IFIT3 plus DV infection worked synergistically to induce a significant increase in cell death." (PMID 24223959, 2013). "According to the accumulation of IFIT3 mRNA, analysis of whole cell lysates by immunoblotting also confirmed accumulation of IFIT3 protein during infection over time." (PMID 21933386, 2011). "Some of these genes like, Oasl2, Oas1a, Oasl1, G1p2, Ifit3 and Iigp2 showed significant regulation at an early phase of infection and these results were consistent with our earlier report on host response in neuronal cell infected with JEV." (PMID 21371334, 2011). "We again used IFIT3-/- cells, expressing the desired IFIT3 via transfection prior to infection." (PMID 40497724, 2025). "Compared to cells expressing WT IFIT3, viral gene expression was significantly reduced during the early stages of infection in cells expressing IFIT3 K249E, and this correlated with a drop in viral spread at later times of infection." (PMID 40497724, 2025). "Both infected and bystander cells were able to respond to infection, producing IFIT3." (PMID 38384473, 2024). "Expression profiles of genes, IFIT2 and IFIT3, were similar throughout the infection." (PMID 39162558, 2024). "Moreover, transcription of the IRF3-dependent genes Ifit3 and Rsad2 was significantly increased upon infection with MCMV M35stop compared to MCMV REV." (PMID 37289084, 2023). "However, amounts of IFIT2 and IFIT3 appear to be slightly higher in B/Yamagata infections with an exceptionally strong band in B/Baltimore/R0337/2018 infection." (PMID 37766362, 2023). "Similarly, infection elicited an increase in IFIT3 protein expression by osteoblasts over constitutive levels as determined by immunoblot analysis and specific capture ELISA." (PMID 36532419, 2022). "During E30 infection, genes associated with the type I IFN signaling pathway (Isg15, Mx1, Mx2, Sp100, Ifit1, Ifit3, Ifih1, Irf7, Irf9, guanylate-binding proteins 2 [Gbp2], and Stat1) and defense response to viruses (Ddx58, Ddx60, Zbp1, Oas2, Nlrc5, and Eif2ak2) were significantly upregulated." (PMID 36147849, 2022). "These nPro/HFs and V/HFs were recently utilized, alongside IRF3 KO CRISPR/Cas9 HFs, to demonstrate that expression of viperin, ISG15, IFIT1, IFIT2, IFIT3, Mx1, and Mx2 mRNA during infection with HCMV can be induced in an IRF3-dependent, STAT1-independent manner." (PMID 31921100, 2019). "Along with IFIT2, IFIT1 and IFIT3 were also increased following infection with both strains." (PMID 29085037, 2017).
infection (continued). "Accordingly, IFIT3 protein levels accumulated during the time course of infection." (PMID 21933386, 2011). "Cluster 1 was more heterogenous and lacked a distinct transcriptional profile, whereas Type I IFN (Isg15, Ifi206, Ifit3, Ccl5) and proliferative signatures (Cdk1, Mki67, Tuba1b) were observed in clusters 3 and 5, respectively, whose numbers remained stable between days 7 and 14 after infection." (PMID 39989461, 2025). "The IFIT3 inhibitor exhibited comparable inhibitory efficacy on the IFIT3 protein in H1975 cells that were injected into the lungs of nude mice at 3 and 6 weeks after infection, with notably elevated levels of distribution observed in the lungs compared to other organs." (PMID 39303913, 2024). "Hence, the genes Ccl2, Ch25 h, Ifit3, Il1rn, Il6, Parp14, Ptx3, and Socs3 can be defined as a common core of genes expressed early in response to local infection and inflammation caused by Gram-negative stimuli." (PMID 21338499, 2011). "Among others, 2’-5’ oligoadenylate synthetase-like (OASL), Interferon induced protein with tetratricopeptide repeats 2, 3 and 5 (IFIT2, IFIT3, IFIT5) were up-regulated in female-derived macrophages upon infection." (PMID 40794782, 2025). "Of these genes, 6 (OASL, IFI27, IFIT1, IFIT3, RSAD2and IFI44L) were in protein-protein interaction network and at each stage of infection." (PMID 40255307, 2025). "Following infection of PAMs with ASFV-WT and ASFVΔMGF360–4L, IFIT2, IFIT3, and IFIT5 transcription were significantly up-regulated." (PMID 41153955, 2025). "We identified 6 genes found to be common in all three levels of infection whose expression level increases withthe increase in the level of infection (OASL, IFI27, IFIT1, IFIT3, RSAD2, IFI44L)." (PMID 40255307, 2025). "According to the previous study, the identified 6 genes were found to be common in all three levels of infection whose expressionlevel increases with the increase in the level of infection (OASL, IFI27, IFIT1, IFIT3, RSAD2 and IFI44L)." (PMID 40322700, 2025). "Some other infection-responsive genes like IFI144, MX1, MX2, IFIT3, and HLA-DOA were also observed proximal to those altered ERVs, and showed positive co-expressions with their proximal ERVs, wherever they located." (PMID 40176799, 2025). "Only five DEPs were common for both infections in both upper and lower trachea, including four interferon stimulated proteins (OASL, MX1, IFIT3, and ISG15) and the GTPase, DRG2." (PMID 39247193, 2024). "In individuals affected by influenza virus infection, IFFI44L, ISG15, IFIT3, and RSAD2 are crucial antiviral factors inhibiting infection within alveolar basal epithelial cells." (PMID 38601162, 2024). "One possible explanation for IFIT3 overexpression in certain individuals could be the presence of genetic variations or epigenetic modifications that enhance IFIT3 expression in response to viral exposure without causing symptomatic infection." (PMID 39664492, 2024). "As a result, we have focused on four down-regulated and immune-related proteins including STAT1, GBP4, IFIT3 and DDX58 after tachyzoite infection." (PMID 37721957, 2023). "The previous research reported that IFIT1, IFIT2, IFTI3, IFIT3, IFI44, HERC4, and OASL genes are antitumoral effects and modulated the inflammatory response in cancer and infection." (PMID 35941292, 2022). "The results showed that more autophagosomes were observed in HP-PRRSV-infected MVECs, and the expression of IFN-α, IFIT3, and IFIT5 decreased or increased at different time points after infection." (PMID 36146725, 2022). "We used qPCR to validate the SARS‐CoV‐2 infection‐dependent upregulation of the IFN‐γ target genes CXCL11 and IFIT3, as well as KRT20 and ACE2 and indeed confirmed an upregulation of these genes upon infection." (PMID 33544398, 2021).
infection (continued). "There was higher expression of IFN-β, IFIT1, IFIT3, ISG15, and IRF7 mRNA in A549 XRN1 KO cells after 8 h of infection with various virus strains, including WSN (H1N1), PR8 (H1N1), CA04 (H1N1), and HK4801 (H3N2)." (PMID 34311580, 2021). "p62 knockdown significantly reduced levels of IRF7, ISG15, IFIT1, IFIT2, and IFIT3 genes, suggesting that p62 was required for maximal activation of the innate immune response during KSHV primary infection." (PMID 33414399, 2021). "In the presence of HO infection, the stimulatory effect of IFNT on expression of GBP4, ISG15, HERC5, RSAD2, IFIH1, IFIT3, and MX1 was significantly reduced (IFNT vs. IFNT+HO, P < 0.05–0.01)." (PMID 33898551, 2021). "Infection with either HO or KY alone had similar inhibitory effects on most ISGs (ISG15, GBP4, HERC5, RSAD2, DDX58, and IFIT3), although a slightly greater inhibitory effect of HO was observed on IFI27 and MX1." (PMID 33898551, 2021). "The stimulatory effect of IFNT on RSAD2, IFIT3 and MX1 was inhibited to a greater extent by HO infection and only HO inhibited GBP4 and HERC5 expression." (PMID 33898551, 2021). "Upon fetal infection, a set of core responsive IFN-inducible genes (CXCL10, IFIH1, IFIT1, IFIT3, ISG15, and MX1) were strongly upregulated in both tissues." (PMID 33148169, 2020). "Three of these genes: IFIT2/ISG54/p54/cig42, IFIT3/ISG60/p60/cig49 and viperin/cig6, were upregulated by HCMV at 8 h post infection (hpi) and even accumulated following exposure to replication-incompetent ultraviolent-irradiated HCMV (UV-HCMV)." (PMID 31921100, 2019). "The up-regulated TF ZFHX3 targets seven genes in module AD_M25, where two genes OAS1 and RSAD2 are detected in infection pathways, and the other five genes FAM122B, SAMD9, TRIM21, USP18 and IFIT3 are also known to be related to infectious disease." (PMID 30598117, 2018). "As expected, infection with rTHOV-ΔML and rTHOV-SW elicited expression of IFIT1 and IFIT3, whereas their expression in rTHOV-wt sample was ~50 fold lower." (PMID 29709033, 2018). "The expression levels of some ISGs (IFIT1, IFIT2, IFIT3) and proinflammatory cytokines (IL-6, IL-8) in DDX1-knockdown cells were analyzed after TGEV infection." (PMID 28848548, 2017). "For example, highly susceptible strains (C57BL/6J, 129S1/SvlmJ, CAST/EiJ) exhibited a strong increase in IFIT3 and IFIT44 expression after infection but only a relatively low increase in expression was observed in the resistant strain PWK/PhJ." (PMID 27193691, 2016). "IFIT1 binds to the free 5′-ppp moiety on RNA of a number of viruses, including influenza A virus, and inhibits infection by forming a complex with IFIT2 and IFIT3 that sequesters viral nucleic acid." (PMID 25191744, 2014). "In the present study, the IFN-stimulated genes (IFIT1, IFIT3, MX1, ISG15, OAS1, and IFI6) were dramatically increased at 16 h and 24 h post infection, which should trigger powerful antiviral functions." (PMID 23527143, 2013). "Further analysis of IFIT3 and XRN2 that were found to be up-regulated during infection were validated on the transcriptional level." (PMID 21933386, 2011). "With the insertion of K1L and C7L, this response was tempered; infection with NYVAC-C-KC-ΔB8RΔB19R induced increased transcriptional levels of seven of the genes shown, relative to NYVAC-C-KC (IFI35, IFI44, IFI44L, IFIT1, IFIT3, IFITM1, and IFITM2)." (PMID 22096477, 2011). "All three selected ISGs namely Mx1, IFIT3 and ISG15 were induced after infection with BADwt." (PMID 40143353, 2025). "We found that, in addition to a broad induction of ISGs (for example, DTX3L, OAS3, RTP4, IRF7, MX2, IFIT3, IFIH1), only IFNB1 and, more robustly, IFNL1-like and IFNL3-like were induced in virus-infected organoids at 1 and 3 days after infection compared to the uninfected controls." (PMID 40399606, 2025).